NPHS2 (NPHS2 stomatin family member, podocin)
Diseases named in the same sentence as NPHS2 in open-access papers (continued):
Sharing a sentence is not in itself a finding about the gene and the disease.
nephrosis (3 papers, 2008 to 2022). Pathological processes of the KIDNEY without inflammatory or neoplastic components. "Homozygous or compound heterozygous mutations in the podocin gene NPHS2 are found in 10–30% of pediatric cases of steroid resistant nephrosis and/or FSGS." (PMID 18823551, 2008). "Here, 15 genes were expressed differently in NaCl vs. HMLS, with hemoglobin subunit beta (Hbb) and nephrosis 2 idiopathic steroid-resistant (Nphs2) also down-regulated to 0.238 and 0.240-fold, respectively." (PMID 34948210, 2021).
Alport syndrome (2 papers, 2024 to 2026). A rare renal disease characterized by glomerular nephropathy with hematuria progressing to end-stage renal disease (ESRD), frequently associated with sensorineural deafness, and occasionally with ocular anomalies. "Other researchers have performed quantitative measurement of urinary podocyte-specific mRNAs, and showed correlations between relative increases of NPHS2 mRNA excretion and disease severity and progression in patients with MCD/FSGS and Alport syndrome." (PMID 41542111, 2026).
glomerulonephritis (2 papers, 2019 to 2022). A renal disorder characterized by damage in the glomeruli. "In this current study, by generating the NPHS2; mT/mG transgenic mice to build the adriamycin-induced glomerulonephritis model, we were able to investigate the molecular mechanism underlying podocyte cell cycle re-entry in vivo precisely." (PMID 30858353, 2019). "The current study traced podocyte cell cycle changes both in adriamycin-induced glomerulonephritis mouse model built by NPHS2 Cre; mT/mG transgenic mice and in isolated primary podocytes treated with adriamycin." (PMID 30858353, 2019). "We then induced an immune‐mediated severe glomerular insult, the anti‐glomerular basement membrane glomerulonephritis model (anti‐GBM‐GN) in 3‐month‐old control and NPHS2‐Cre+/− mice." (PMID 36082952, 2022).
Hypertension (2 papers, 2019 to 2021). The presence of chronic increased pressure in the systemic arterial system. "Early after genetic Nphs2 deletion, sodium retention occurred, followed by hypertension and gross proteinuria." (PMID 31368174, 2019). "Characterizing the mouse model of podocyte inactivation of NPHS2 (Nphs2∆pod) with respect to volume handling and proteinuria revealed that sodium retention, hypertension and gross proteinuria appeared sequentially in a chronological order." (PMID 31368174, 2019). "The proband (II-1) displayed an NPHS2 polymorphism c.725C>T (p.Ala242Val) manifested as hematuria, persistent proteinuria (1500 mg/l), and normal renal function, while the father (I-1) of the proband had no history of hematuria, proteinuria, hypertension, or CKD." (PMID 33305316, 2021).
nephrotic syndrome, type 2 (2 papers, 2015 to 2019). Any nephrotic syndrome in which the cause of the disease is a mutation in the NPHS2 gene. "The remaining two were in the non-CLA-related genes NPHS2, responsible for nephrotic syndrome type 2 and SLC16A1, which encodes a monocarboxylate transporter (MCT1), that mediates the movement of lactate and pyruvate across cell membranes." (PMID 31683770, 2019).
amyloidosis (1 paper, 2019). A disorder characterized by the localized or diffuse accumulation of amyloid protein in various anatomic sites. "Given the sentence, "Hsf-1 affects podocyte markers NPHS1, NPHS2 and WT1 in a transgenic mouse model of TTRVal30Met-related amyloidosis," three entity relations, with relation type and biological context, were extracted by the context-based ABC model." (PMID 31017923, 2019).
benign familial hematuria (1 paper, 2019). "NPHS2+/R140Q mice develop no phenotype, while COL4A3+/− mice develop benign familial hematuria." (PMID 30691124, 2019).
familial hematuria (1 paper, 2017).
gout (1 paper, 2024). A condition characterized by painful swelling of the joints, which is caused by deposition of urate crystals. "Importantly, the RV rs559954634 positively affects gout, and its neighboring gene NPHS2 is involved in serum urate and expressed in kidney tissues." (PMID 39385933, 2024).
microcephaly (1 paper, 2025). A congenital or acquired developmental disorder in which the circumference of the head is smaller than normal for the person's age and sex. "Of the reported participants with the NPHS1 variant (NM_004646.4:c.106 delG), one had extra renal manifestations, which include microcephaly and pulmonary valve stenosis, while the one with the NPHS2 NM_004646.4:c.781G>T variant presented with pulmonary artery stenosis." (PMID 41300747, 2025).
renal hypertension (1 paper, 2024). Hypertension caused by the kidney's hormonal response to narrowing or occlusion of the renal arteries. "Furthermore, in mice with renal hypertension induced by NPHS2 gene knockout, western blot and immunohistochemical staining analyses revealed a notable increase in CTSB expression in podocytes, glomeruli and intercalated cells." (PMID 39248527, 2024).
thin basement membrane nephropathy (1 paper, 2008). "Rare NPHS2 alleles have also been demonstrated in subjects with thin basement membrane nephropathy (TBMN)." (PMID 18823551, 2008).
kidney disease (20 papers, 2011 to 2024). "They include numerous genes associated with kidney diseases, such as Chga/Chgb, Ptprn, Nphs1/Nphs2, Nsf, Rph3a, Podxl and Cyp11a1." (PMID 36130284, 2022). "In one of the three probands an hypomorphic variant in NPHS2 was also found, suggesting that role of other kidney disease related-genes as modifiers." (PMID 30808327, 2019). "Disorders in Nphs2, Cat, and Rgn genes are associated with kidney diseases." (PMID 35140605, 2021). "Similarly, other genes such as nephrin (NPHS1) and podocin (NPHS2) contribute to the loss of renal function during renal diseases." (PMID 21859496, 2011). "Contrary to NPHS2 and AHR, which is a well-known gene involved in kidney function, the role of CHCHD4 in kidney disease has not been studied as much." (PMID 37510393, 2023).
genetic disease (4 papers, 2017 to 2024).
infection (2 papers, 2022). The state of being infected such as from the introduction of a foreign agent such as serum, vaccine, antigenic substance or organism. "The transcriptome of the tubular epithelial- and podocyte-specific genes, AQP1, AQP6, NPHS2, SCL12A1, was examined over a period of 11 days for toxic and ischemic and of up to 24 days for nephritic and infection-associated AKI." (PMID 36285332, 2022). "No significant changes in the levels of expression of podocyte marker genes (WT1, PODXL, NPHS1, NPHS2, and MAFB) or for tubular marker genes (SLC3A1 and SLC16A1) were found after infection comparing WT and ACE2 KO kidney organoids." (PMID 35561674, 2022).
autosomal recessive disease (1 paper, 2014). Autosomal recessive form of disease. "Most cases of CNS are autosomal recessive diseases caused by genetic defects in different components of the glomerular filtration barrier (primary CNS), especially by mutations in nephrin (NPHS1, nephrotic syndrome type 1) and podocin (NPHS2) genes." (PMID 24682440, 2014).
immune disorder (1 paper, 2017). "As regards to the non-syndromic forms, some are related to a still not completely understood underlying immune disorder, while an increasing number is found to be caused by mutations in genes highly expressed in podocytes (e.g. NPHS1, NPHS2, CD2AP, PLCE1, ACTN4, TRPC6, and INF2)." (PMID 28298181, 2017).
mitochondrial disease (1 paper, 2019). "For example, in patients Pt11 and Pt22, who met the criteria for mitochondrial disease with relatively high MDC scores, DNA analysis identified biallelic changes in NPHS2 and SLC16A1, which might be a phenocopy of mitochondrial disease." (PMID 31683770, 2019).
NPHS2 also shares sentences with these, for which no sentence is quoted: autosomal dominant polycystic kidney disease (2 papers); familial hypercholesterolemia (2); Methylmalonic aciduria (2); (LCHAD) deficiency (1); absence seizures (1); Atrophy (1); Bartter syndrome (1); ciliopathies (1); cognitive decline (1); Dent disease (1); Denys-Drash syndrome (1); Fabry disease (1); familial episodic pain syndrome (1); Hereditary breast and ovarian cancer syndrome (1); Hyperglycemia (1); hypertrophic cardiomyopathy (1); Hypomagnesemia (1); lactic acidosis (1); microhematuria (1); mitochondrial encephalomyopathy (1); nephritis (1); Progressive encephalopathy (1); Pulmonary artery stenosis (1); pulmonary valve stenosis (1); sickle cell disease (1); Stroke (1).